ERBB2 (erb-b2 receptor tyrosine kinase 2)
Diseases named in the same sentence as ERBB2 in open-access papers (continued):
Sharing a sentence is not in itself a finding about the gene and the disease.
breast cancer (continued). "Human epidermal growth factor receptor-2 (HER2) encoded by oncogene ErbB2, exhibits amplification and over-expression in 20%–30% of breast cancer cases." (PMID 39346561, 2024). "ERBB2 (also known as HER2) is a receptor tyrosine kinase that is often overexpressed in breast cancer and has been implicated in the development of FMC as well." (PMID 39330508, 2024). "The majority of the tumors were discovered to be mammary carcinomas with overexpressed HER‐2/ErbB2 and inactivated wild‐type FOXP3 alleles." (PMID 38827026, 2024). "In breast carcinoma cells, when Sema4D binds to Plexin-B1 associated with ErbB2, it induces cell migration and metastasis." (PMID 39769452, 2024). "Several studies have reported that serum ERBB2 is associated with breast cancer prognosis and can be used to monitor treatment responses." (PMID 37174100, 2023). "Grb2 is an adaptor protein that can associate either directly or indirectly with ErbB2, an oncogene associated with poor survival in breast cancer patients." (PMID 37242677, 2023). "As these studies focus on breast cancer, further investigation of the mutational landscape of HER2low mCRCs with a focus on upstream regulators of ERBB2 is needed." (PMID 38138928, 2023). "Two of them, PIK3CA H1047L and ERBB2 V777L, are well-known mutations, which often occur in breast cancers and lead to the activation of the respective protein." (PMID 36823365, 2023). "Approximately 15% of breast cancers (BCs) harbour an amplification of the ERBB2 gene, which encodes human epidermal growth factor receptor 2 (HER2)." (PMID 36900178, 2023). "The association between ERBB2 and poor prognosis in breast cancer is well established and led to the development of ERBB2-targeted therapies." (PMID 37064102, 2023). "In a phase II trial involving 125 patients with ERBB2 mutations across 21 cancer types, treatment with neratinib, a pan HER2-TKI, provided a 24% response rate among breast cancer patients with ERBB2 S310, L755, V777, G778_P780dup and Y772_A775dup mutations." (PMID 36980614, 2023). "In mice with ErbB-2-induced breast cancer, PTP1B deficiency or inhibition delayed tumor progression, protected against lung metastases, and triggered earlier apoptosis by down-regulating both Ras-MAPK and PI3K-Akt signaling pathways." (PMID 37298571, 2023). "ErbB2 is the most over-expressed receptor in ~30% of breast cancer cases and is associated with poor prognosis." (PMID 38203605, 2023). "On the other hand, its overexpression is associated with HER2‐positive breast cancers and increased levels of ERBB2." (PMID 37718413, 2023). "There is ample evidence that EGFR1 (ErbB1) functionally interacts with ErbB2 and is linked to tumour growth, especially in breast cancer." (PMID 38203605, 2023). "The silencing of STAT3 in MCF7-HER2 breast cancer cells also reduced their ability to form tumorspheres caused by the overexpression of Erb-b2 receptor tyrosine kinase 2 (ERBB2) that encodes HER2." (PMID 38067351, 2023). "We then used MCF7 breast cancer cells with doxycycline (dox)-inducible expression of NeuT, an oncogenic HER2/ERBB2 variant." (PMID 36670508, 2023). "Amplification/overexpression of HER2 (also known as erbB2/neu) is significantly associated with poor prognosis in breast cancer (BC) patients." (PMID 37370010, 2023). "The same finding was made in ERBB2+ trastuzumab-resistant breast cancer, in that the control of ERBB2 leads to loss of kinases such as WNK1 and YES1 implicated in this cancer mechanism of resistance." (PMID 37359373, 2023). "The co-mutation of CDH1 with PIK3CA and ERBB2 contributes to endocrine resistance in breast cancer patients with invasive lobular carcinoma." (PMID 37426414, 2023). "We took the three targets with highest predicted probability; ERBB4 (0.790), EGFR (0.784) and ERBB2/HER2 (0.724) all known to be expressed in HER2 + breast cancer, to the causal reasoning analysis stage." (PMID 37715141, 2023).
breast cancer (continued). "Ethanol stimulates invasion of breast cancer by overexpression of ErbB2, which is positively associated with elevated levels of matrix metalloproteinases." (PMID 36310188, 2023). "In this retrospective cohort study, we compared clinical outcomes in the I-SPY 2 trial across patient racial groups among women with clinically (ERBB2-positive or HR-negative) or genomically (based on MammaPrint molecular subtyping) high-risk breast cancer." (PMID 38153734, 2023). "Enhanced HER3 expression was also reported to cause paclitaxel resistance in erbB2-overexpressing breast cancer cells via the upregulation of Survivin." (PMID 37947595, 2023). "In a clinical trial, the use of anthracycline for patients with ERBB2 (formerly HER2)-positive breast cancer in the presence of double ERBB2 blockade will increase the risk of febrile neutropenia and cardiotoxic effects." (PMID 37153795, 2023). "In breast cancer, ERBB2 mutations have been described in all histological subtypes, usually in the absence of ERBB2 amplification." (PMID 36980614, 2023). "Estrogen receptor (ER), progesterone receptor (PR), and human epidermal growth factor receptor-2 (ERBB2/HER2) are considered as the molecular markers for diagnostic classification of breast cancer subtypes." (PMID 37813891, 2023). "The second model (FVB strain erbB2 (HER2) mutant mice, genetically susceptible to mammary tumors fed regular chow) showed that oral supplementation with L. reuteri was also sufficient to inhibit features of mammary neoplasia." (PMID 37664075, 2023). "Approximately 15–20% of breast cancers are characterized by an oncogenic amplification of the ErbB2 gene, encoding the HER2 transmembrane protein." (PMID 37561255, 2023). "Consistent with the literature, we found that from all of the cancer sub-tissues, breast cancer contributed the most to the Sen-Scoreglobal of ErBb2, as high ErbB2 expression was significantly associated with sensitivity to 62% of the drugs in the ErbBs sign." (PMID 37508418, 2023). "Clinical trials have shown an enhanced benefit with combined endocrine and HER2-directed therapies in patients with HR+/HER2+ or ERBB2-mutated breast cancers." (PMID 37258523, 2023). "In patients with breast cancer, ERBB2 is a crucial biomarker for improving diagnostic accuracy and therapeutic outcomes." (PMID 37174100, 2023). "In this work, we describe the capability of the PPRH technology to produce gene silencing of the ERBB2 gene expression in breast cancer cells, causing a significant decrease in in vitro cell viability and in vivo tumor growth." (PMID 37108234, 2023). "In particular, rs1136201 (A>G) in ERBB2, also referred to as the HER2 Ile655Val polymorphism, has been investigated as a susceptibility factor for breast cancer because Val-expressing cells exhibit increased proliferation and reduced apoptosis in vitro." (PMID 37120792, 2023). "ERBB-2/Her-2 alterations (overexpression, amplification, or point mutations) are common in breast cancer patients, where the monitoring of ctDNA under treatment has shown a high predictive value regarding the response to therapy." (PMID 36900221, 2023). "This includes 2 patients with MSI-high tumors with the indication for checkpoint immunotherapy, 2 patients with ERBB2 amplification in the context of possible breast carcinoma, as well as 1 patient with IDH1 mutation." (PMID 36933203, 2023). "We apply multiplexed QASeq to serial longitudinal plasma cfDNA samples from patients with metastatic ERBB2+ (HER2+ ) breast cancer seeking association with tumor progression." (PMID 35379811, 2022). "Snai2 is also associated with a poor prognosis of luminal B HER2+/ERBB2+ breast cancers and directly contributes to cisplatin resistance in ovarian cancer." (PMID 35631574, 2022). "We have reported previously that PTPRO promoter hypermethylation is associated with poor survival for patients with ERBB2-positive breast cancer." (PMID 35431974, 2022).
breast cancer (continued). "TXNRD1 and thioredoxin interacting protein (TXNIP) were associated with poor breast cancer prognosis, and ERBB2 was suggested to play a role in altering their redox control pathway." (PMID 35158912, 2022). "ERBB2 is found to be amplified in a number of tumor types of epithelial origin including lung, gastric and bladder cancers and is a major cause of breast cancers, accounting for 15% of cases where amplification drives aggressive and invasive tumor formation." (PMID 36076950, 2022). "HER2 expressed in HER2-enriched and part of luminalB breast cancer is the membrane receptor encoded by the proto-oncogene ERBB2, which is a member of human epidermal growth factor receptor (EGFR/ERB) family of tyrosine kinase receptors." (PMID 35311116, 2022). "For example, ERBB2 (Her2) amplification is considered prognostic in breast cancer and CDKN2A deletion is considered diagnostic and prognostic in glioblastoma." (PMID 35251754, 2022). "Alterations of ERBB2 including gene amplification, protein overexpression, and missense mutations have been reported in multiple solid cancers, especially in breast cancer, stomach cancer, and non-small cell lung cancer (NSCLC)." (PMID 35911441, 2022). "Activating mutations in the HER2/ERBB2 gene are another mechanism of resistance to HER2-directed therapies; these are found in around 2–3% of all breast cancers and are associated with a worse prognosis." (PMID 36010990, 2022). "About 15–20% of all breast cancer cases display an amplification and/or overexpression of the ERBB2 gene, which encodes the human epidermal growth factor receptor 2 (HER2), and are referred to as “HER2-positive breast cancer”." (PMID 35454795, 2022). "The system can further detect the exosomal ERBB2 in the blood associated with breast cancer, thus proving the validity of the system in the diagnosis of breast cancer." (PMID 35214519, 2022). "Since ERBB2 (encodes the HER2 protein) is amplified in ~20% breast cancers, one can instead assess ERBB2 copy number amplification from ctDNA genomic analysis." (PMID 36463275, 2022). "Murine hearts deficient in ErbB2 and/or ERRα are used to profile the adverse cardiac remodeling associated with potential targeted breast cancer treatments by phosphoproteomic, transcriptomic and metabolomic profiling." (PMID 36097051, 2022). "Other alterations that can lead to hyperactivation of the PI3K pathway in breast cancer include ERBB2 and AKT mutations, and deletions, nonsense and loss-of-function missense mutations in the tumor suppressor PTEN." (PMID 35774123, 2022). "While ERBB2 activating mutations are uncommon in primary breast cancer they are enriched in recurrent tumors." (PMID 36045910, 2022). "Its overexpression and/or the amplification of its encoding gene, ERBB2, is also associated with poor response to chemotherapy and increased recurrence rate in breast cancer." (PMID 35335898, 2022). "It has been reported that high expression of CSF1R is related to breast cancer progression and that high rates of ErbB2 is linked to lower overall survival rates." (PMID 36014478, 2022). "Gene expression signatures of ERBB2 alterations are historically well-studied in breast cancer, and samples with activating ERBB2 mutations have recently been shown to share sensitivities to some small-molecule inhibitors across cancer types." (PMID 35761387, 2022). "The discovery that amplification or overexpression of ERBB2 was associated with extremely poor survival in breast cancer led to efforts that resulted in the development of a monoclonal antibody (mAb) to HER2, trastuzumab." (PMID 36612126, 2022).
breast cancer (continued). "Approximately 15% of breast cancers display an amplification of ERBB2, which encodes the human epidermal growth factor receptor 2 (HER2) and is associated with poor prognosis." (PMID 35565244, 2022). "For example, subtype heterogeneity has been identified when investigating the specific effects of a polygenic risk score and breastfeeding for breast cancer subtypes: basal-like and ERBB2 (HGNC ID: 3430; so-called HER2)-overexpressing breast cancer." (PMID 35406583, 2022). "The ERBB2 L755S alteration has been implicated in HER2-targeted therapy resistance in breast cancer." (PMID 36191033, 2022). "ER and PR expression were negatively associated with receptor-tyrosine kinase erbB-2 (HER2) expression in postmenopausal patients with breast cancer." (PMID 35712498, 2022). "ERBB2 encodes a membrane receptor in the epidermal growth factor receptor family, is a key breast cancer marker, and involves in breast cancer metastasis." (PMID 36418351, 2022). "Meanwhile, ERBB2 (erb-b2 receptor tyrosine kinase 2) is a member of the epidermal growth factor (EGF) receptor family genes encoding for well-known HER2 protein, which is known to play an essential role in breast cancer progression and treatment selection." (PMID 36009413, 2022). "This CSAGA is linked to the amplification of 17q11.2 genomic regions and is associated with the expression of ERBB2 in breast cancer." (PMID 36425112, 2022). "ERBB2, amplified in 20%–30% of the breast cancer cases, is associated with aggressive tumor behavior." (PMID 36276102, 2022). "We demonstrate that the E1A coded by oAd/shErbB, in contrast to dAd/shErbB, caused downregulation of ErbB2 and ErbB3, yielding stronger downregulation of the ErbB3-oncogenic signaling axis in in vitro models of lung and breast cancer." (PMID 35806132, 2022). "Clinically, the expression of the human epidermal growth factor receptor 2 (HER2, also known as the erb-b2 receptor tyrosine kinase ERBB2) has been linked to taxane therapy responses in breast cancer patients." (PMID 35281802, 2022). "Mutations have been observed in each domain, but overall, ERBB2 mutations occur in less than 5% of breast cancer patients." (PMID 36276152, 2022). "A number of studies have identified the expression of lncRNA HOTAIR in the blood of breast cancer patients where it was associated with the high expression of ERBB2 (Receptor tyrosine-protein kinase)." (PMID 36685962, 2022). "We found that in a cohort of 398 patients with ErbB2/Her2-positive breast carcinoma, increased BLNK mRNA expression is significantly associated with increased disease-free survival: p-value = 0.0018, hazard ratio = 0.6 (95% CI 0.43–0.83)." (PMID 35933456, 2022). "ERBB2 gene, commonly referred to as HER2, is overexpressed or amplified in 15% to 30% of breast cancer (BC) cases, and has been historically associated with poor prognosis and a more aggressive cancer phenotype." (PMID 36428742, 2022). "The presence of the H3K4me3 mark in the promoter of the ERBB2 (i.e., HER2) gene is associated with HER2-overexpressing breast carcinomas." (PMID 35454810, 2022). "HER2 overexpression in breast cancer (BC) is strictly connected to the underlying presence of ERBB2 amplification to which they become addicted, providing the basis of successful treatment of these tumors with traditional and novel anti-HER2 agents." (PMID 36038884, 2022). "hTid-1 has been found to be over-expressed in human mammary carcinomas, causing suppression of ErbB2 expression, leading to inhibition of ErbB2-mediated tumor progression." (PMID 35854300, 2022). "Here, we show that EVs released from ERBB2+ breast cancer cells are polymorphic in size and appearance and that ERBB2 is preferentially associated with large (120 nm) EVs." (PMID 33809102, 2021). "In line with this evidence, CD151 expression appears elevated at the mRNA level in metastatic tumors and is associated with poor clinical outcomes in the ErbB2+ breast cancer subtype." (PMID 33919420, 2021).
breast cancer (continued). "HER2/ERBB2 (erb-b2 receptor tyrosine kinase 2), a member of the epidermal growth factor receptor family, is amplified/overexpressed in 15–20% of breast cancers and associated with poor prognosis." (PMID 33903614, 2021). "Similar results were present in the case of the ERBB2 gene, which encodes a cell surface protein-tyrosine kinase receptor that is associated with the progression of breast cancer 20 and higher expression of genes in the Wnt-β-catenin pathway." (PMID 33723286, 2021). "For example, the ERBB2/PIK3/AKT/mTOR pathway is known for its relevance in breast cancer, but recently a relevant actionable mutation from the same pathway, PIK3R1W624R was also identified in ovarian cancer." (PMID 33277683, 2021). "Dysregulation of MYC has also been shown to be involved in genome instability, where MYC amplification has been reported to be closely linked to ERBB2 proto‐oncogene (mapped to 17q12) amplification to strongly activate cell proliferation in breast cancer." (PMID 34954904, 2021). "A systematic review revealed that the frequency of ERBB2 mutations in breast cancer (BC) is relatively low (2.7%)." (PMID 34257600, 2021). "ERBB2 overexpression is highly associated with poor prognosis in breast cancer, and the Food and Drug Administration has designated ERBB2 as an efficient therapeutic target." (PMID 33530560, 2021). "HER2 receptor tyrosine kinase (encoded by the ERBB2 gene) is overexpressed in approximately 25% of all breast cancer tumors (HER2-positive breast cancers)." (PMID 34575017, 2021). "A splice variant of ERBB2 that removes exon 16 in the extracellular domain of HER2 (d16HER2) has been described in breast cancers and HER2+ cell lines." (PMID 35008318, 2021). "ERBB2-associated morphology correlated with the efficacy of adjuvant anti-ERBB2 treatment and can contribute to treatment-predictive information in breast cancer." (PMID 33597560, 2021). "This is clinically important as case reports have shown that patients with ERBB2-mutated breast cancers respond to targeted HER2 targeted therapy." (PMID 33441174, 2021). "For the next common core signaling pathway, the receptor ERBB2, which was mutated in breast cancer, received microenvironment factor CCL28 to activate TF BRCA1 through signaling transduction proteins CDC42 and ARRDC3 in TNBC and non-TNBC." (PMID 33802957, 2021). "Oleic acid also prevents breast cancer cells from proliferating by inhibiting the growth of cancer-causing oncogenes HER-2/neu (erbB-2) expression." (PMID 34960117, 2021). "A total of 205 ERBB2 aberrations were detected in 175 of the 589 breast cancer cases, revealing an ERBB2 mutation rate of 29.7%." (PMID 33968723, 2021). "In non-ErbB2-overexpressing breast cancer cell lines, loss of CHIP expression was shown to increase the expression of transcriptional co-regulator SRC-3, with increased expression of pro-oncogenic proteins such as Smad2 and twist, to promote metastasis." (PMID 34439093, 2021). "PDK1 is required for the activation of AKT, and increased PDK1 expression in breast cancer is associated with ERBB2 amplification and PIK3CA mutations." (PMID 33933113, 2021). "Here, we assessed the effect of intratumor cellular genetic heterogeneity for ERBB2 (encoding HER2) copy number and PIK3CA mutation on different types of neoadjuvant HER2-targeting therapies and clinical outcome in HER2+ breast cancer." (PMID 33886505, 2021). "The receptor is encoded by the ERBB2 gene, which is amplified in about 20% of all breast cancer patients." (PMID 34035375, 2021).